ENSG00000252119
Synonyms: LOC124900316
Gene: Small nucleolar RNA gene on chromosome 11 (119,323,293 to 119,323,409, reverse strand). Ensembl gene ENSG00000252119.
Gene Ontology:
Biological process: RNA processing
Cellular component: nucleolus
Homologues: Orthologues: mouse Snora78 (77% identical), rat LOC120095472 (77% identical). Paralogues in human: SNORA78 (85% identical).